WDR4 (WDR4 tRNA N7-guanosine methyltransferase non-catalytic subunit)
Diseases named in the same sentence as WDR4 in open-access papers (continued):
Sharing a sentence is not in itself a finding about the gene and the disease.
neurodevelopmental disorder (3 papers, 2020 to 2025). A behavioral and cognitive disorder with onset during the developmental period that involves impaired or aberrant development of intellectual, motor, or social functions. "Through WES, various WDR4 mutations were identified in patients with neurodevelopmental disorders." (PMID 36681682, 2023). "Thus, our study establishes a mouse model for WDR4 mutation-related neurodevelopmental disorders and provides mechanistic insights into these disorders." (PMID 36681682, 2023). "Yet for all we know, it remains unclear whether impairment of any of these functions is responsible for the neurodevelopmental disorders observed in the WDR4-mutated patients." (PMID 36681682, 2023). "Importantly, CG33172, TRM734 and WDR6 are members of the WD40-repeat-containing domain superfamily that contains also the human protein WDR4, another tRNA-MTase cofactor that, like FTSJ1, when mutated is associated with neurodevelopmental disorders." (PMID 31943105, 2020).
digestive diseases (1 paper, 2024). "The METTL1/WDR4 complex can methylate mRNA, tRNA, and miRNA and affect translation, thus playing a role in digestive diseases." (PMID 39850560, 2024). "By modulating the activity of methyltransferases such as METTL1 or WDR4, the level of m7G modification can be altered, thereby regulating the expression of related genes and cellular functions, and offering new hope for the treatment of digestive diseases." (PMID 39850560, 2024). "This review will focus on the latest research progress on the roles of m7G methyltransferase METTL1/WDR4 and recognized enzyme QKI in digestive diseases." (PMID 39850560, 2024).
WDR4 also shares sentences with these, for which no sentence is quoted: squamous carcinoma (3 papers); Encephalopathy (2); glioblastoma (2); pancreatic cancer (2); prostate carcinoma (2); astrocytic tumor (1); brain disorder (1); brain malformations (1); breast tumors (1); colorectal cancer (1); developmental delay (1); digestive system tumors (1); Down syndrome (1); esophageal adenocarcinoma (1); gastric cancer (1); growth deficiency (1); holoprosencephaly (1); Lissencephaly (1); lung adenocarcinoma (1); melanoma (1); neuroblastoma (1); neurological disorders (1); osteosarcoma (1); ovarian serous cystad enocarcinoma (1); Seckel syndrome (1); teratozoospermia (1).